FAP (fibroblast activation protein alpha)
Diseases named in the same sentence as FAP in open-access papers (continued):
Sharing a sentence is not in itself a finding about the gene and the disease.
cancer (continued). "Each cancer type possesses unique molecular characteristics and a distinct TME, which can contribute to the variations in FAP expression." (PMID 37490719, 2023). "FAP-α regulates ECM remodeling, as well as cancer cell invasion and migration 37, while S100A4/FSP1 is involved in angiogenesis, invasion, and metastatic colonization." (PMID 36860926, 2023). "The hOMF highly expresses CAFs markers such as α-SMA and FAP-α after PDGF-BB intervention, while the activated hOMF further promotes the massive secretion of PDGF-BB by cancer cells through refeeding, forming a positive feedback reciprocal loop." (PMID 37365497, 2023). "Biomarkers (FAP, POSTN, PDGFRα/β, FSP-1, CD90, Palladin, OPN, AEBP1, TNC, CD10, and GPR77) represent cancer-promoting CAFs." (PMID 37476379, 2023). "This study also investigated the signaling pathways involved in COL10A1/FAP/FN1, and the results showed that FN1 is a component of the extracellular matrix (ECM), which is a characteristic gene for cancer." (PMID 38063927, 2023). "The tumors were then digested into individual cells, and FACS was used to isolate GFP-expressing cancer cells, CD45+ leukocytes, fibroblast activation protein (FAP)+ fibroblasts, and other cells." (PMID 37296899, 2023). "Among the well-known CAF markers such as smooth muscle actin (SMA) and fibroblast activation protein (FAP), high expression of SMA in the peritumoral stroma has been reported to be a prognostic factor in various cancers." (PMID 38017374, 2023). "In recent years, fluorescent probes targeting FAP such as FTL-S-S0456 and HCFP have been pursued for cancer imaging." (PMID 38026901, 2023). "FAP, which has been utilized as a marker for CAF, is highly upregulated in various cancers and is shown to be a poor prognostic factor." (PMID 36598731, 2023). "To date, several preclinical and case series have been reported on FAP TRT using varying compounds and showing effective and tolerant results in advanced cancer patients." (PMID 36813980, 2023). "We found that both the protein levels of PODNL1 and FAP were higher in TME, and PODNL1 protein was especially highly expressed in cancer cells." (PMID 37504302, 2023). "Moreover, the effect of FAP expression on patient survival may vary across different cancer types." (PMID 37490719, 2023). "Cells that express FAP have been described to induce stromal cell-derived factor 1 (SDF-1) expression, promoting tumorigenesis and immunoreaction in different cancer types such as melanoma and pancreatic ductal carcinoma." (PMID 37175653, 2023). "Recent PET/CT studies with FAP inhibitors have been well developed, revealing strong PET signals across dozens of major cancers, especially digestive system cancers." (PMID 36477400, 2023). "FAP is an established molecular target in nuclear medicine, with several analogues developed for PET imaging specifically in cancer in recent years." (PMID 38004406, 2023). "Because of the expression of FAP-α by CAFs and by some malignant cells, there is heightened interest in targeting FAP-α in cancer." (PMID 36937451, 2023). "The other type of CAF is called inflammatory CAF (iCAF), which is distant from cancer cells and expresses low levels of α-SMA and FAP but secretes high levels of inflammatory mediators, including IL-6." (PMID 37143134, 2023). "The subpopulation of FAP+ACTA2+ CAFs was composed of 276 cells (59.6%) from indolent LUADs and 187 cells (40.4%) from aggressive carcinomas." (PMID 37848457, 2023). "Radionuclide-labeled fibroblast activation protein inhibitors (FAPI) targeting FAP as a tracer for PET imaging have been tested for targeted diagnosis and treatment of cancer." (PMID 35326670, 2022). "Human triple-negative breast and ovarian cancer studies have yielded 3–4 CAF subtypes, designated CAF S1–S4 based on the differential expression of six fibroblast markers (FAP, integrin β1/CD29, α-SMA, S100-A4/FSP1, PDGFRβ, and caveolin-1)." (PMID 36010899, 2022).
cancer (continued). "As FAP is a potential target for cancer treatment, 68Ga-FAPI PET/CT is a promising tool not only for staging but also for guiding potential FAP targeted treatments." (PMID 35326586, 2022). "Several small-molecule inhibitors of FAP (FAPI) were developed and labeled with PET radioisotopes and used in clinical diagnostics of various cancers." (PMID 35471681, 2022). "Currently, the targeted imaging of fibroblast activation protein alpha (FAP), a serine protease expressed mainly by activated fibroblast, is gaining tremendous interest in cancer and inflammatory diseases." (PMID 35733858, 2022). "Another factor attenuating CD8 T cell infiltration is Fibroblast growth factor-β (FGF2) a cytokine released by cancer cells that activates quiescent fibroblasts and upregulates CAF marker expression like αSMA and FAP." (PMID 35479076, 2022). "Most cancers presented PDGFRA, PDGFRB, PDPN, ACTA2, and FAP hypermethylation compared to normal samples." (PMID 36032075, 2022). "In all samples, α-SMA and FAP (as known CAF markers) and interleukin-6 (IL-6) were highly expressed in the fibroblasts surrounding cancer cells." (PMID 35615263, 2022). "Co-expression of FAP and PSMA has been reported for various malignant tumors, including prostate, lung, colorectal, gastric, pancreatic, and thyroid cancers, as well as renal cell carcinomas, sarcomas, lymphomas, and other tumors." (PMID 35337180, 2022). "As a pan-cancer target with an excellent TBR, FAP is considered an attractive target for radionuclide therapy." (PMID 35198057, 2022). "In cancer patients that high FAP expression in CAFs restricts T cell distribution and promotes immune checkpoint blockades (ICBs) resistance, treatment with FAP inhibitor could neutralize the immunosuppressive function of CAFs and reverse anti-PD1 drug resistance." (PMID 35222418, 2022). "Several recently developed quinolone-based FAP inhibitors (FAPIs) coupled to chelators, including gallium-68 (68Ga)-labelled FAPI, are advantageous in staging and restaging many cancers, including peritonitis carcinomatosis, compared with [18F]F-FDG PET/CT." (PMID 36698416, 2022). "First, it has been reported that in GC, CAFs produce fibroblast activation protein alpha (FAP), which promotes cancer progression via EMT through the WNT/β-catenin signaling pathway." (PMID 36465405, 2022). "Together, the abundance and the unique expression of FAP make FAP-expressing CAFs an appealing target for nuclear imaging and TRT with potential pan-cancer application." (PMID 35788730, 2022). "Even in the case of the promoters of the CXCL12, FAP, and SPARC genes, which showed high transcription levels in IVP-9TS as compared to cancer cell lines." (PMID 33804861, 2021). "Recently, a novel immunocytokine, FAP-IL-2v (RO6874281), has been and is continued to be used in clinical trials for PDAC and other cancers." (PMID 33499238, 2021). "During the study of gene transcription in a panel of human cancer cell lines and primary culture of human fibroblasts, we identified the CXCL12 and FAP genes that showed high and specific transcription in fibroblasts." (PMID 33804861, 2021). "Others have shown that CAFs can secrete FAP and α-SMA, thereby creating a favorable environment for cancer cells and enabling the migration and invasion of cancer cells." (PMID 33423167, 2021). "In tissues rich in αSMA and FAP, CCL2 and IL-6 secretion is increased, leading to cancer progression." (PMID 34445235, 2021). "Coercive feedback signaling from cancer cells to CAF does exist, thus assuring the maintenance of FAP production and perpetuating the loop." (PMID 34359555, 2021). "There was also a decrease in CXCL12, a chemokine ligand expressed by FAP+ CAFs that binds to the CXCR4 receptor on cancer cells, diverting T-cells from malignant cancer cells." (PMID 33499238, 2021).
cancer (continued). "Alternatively, highly selective FAP tracers gallium-68-FAPI-02, -04 and -13 display high specificity and have been effectively deployed for theranostic treatment of cancer patients 14-16,37." (PMID 34335962, 2021). "In this international multicenter retrospective analysis, 71 patients with various cancers underwent both 18F-FDG and 68Ga-labeled FAP inhibitors." (PMID 34137945, 2021). "Among them, FAP has received tremendous interest as a potential biomarker for CAF identification and targeting due to its overexpression in most of the cancer types but low to undetectable in normal fibroblasts presented in the body." (PMID 34681246, 2021). "This process provides an enhanced cellular localization of FAP in the actin-rich protrusions on the plasma membrane of malignant cells, which involves the ECM degradation of cancer invasiveness." (PMID 34681246, 2021). "The data suggest that the anti-cancer activity of β-carotene is related to the inhibition of M2 macrophage polarization and fibroblast activation (alpha-smooth muscle actin (α-SMA), fibroblast activation protein alpha (FAP), and TGF-β1)." (PMID 33321708, 2020). "FAP was expressed only in CRC tissue and its expression level was found to be higher in tumors exhibiting deeper local invasion and poorer cancer cell differentiation." (PMID 32428869, 2020). "Fibroblasts from malignant tumors also express proteins that are inhibited in normal tissue fibroblasts, especially α-SMA and FAP." (PMID 30992392, 2019). "The immunostaining of FAP-a in stromal fibroblasts and GOLPH3 in carcinoma cells was scored semiquantitatively as 3 (high), 2 (low), and 1 (absent of staining) based on the staining intensity, respectively." (PMID 31921678, 2019). "Therefore, FAP overexpression might contribute to cancer progression." (PMID 30419872, 2018). "Targeting FAP+ TAF, or αSMA+ myofibroblast has elicited unexpected drawbacks, since these cells can also function as negative regulators of cancer cell growth." (PMID 29515580, 2018). "Stromal expression of α‐SMA, FSP‐1, FAP, and PDGFR‐β were positive stained in CAFs around cancer cells." (PMID 30062820, 2018). "FAPα as a new marker for CTC affinity selection was specific as only a few hematopoietic cells were co-isolated from blood of healthy donors and non-cancer patients." (PMID 29657983, 2017). "Following exposure to cancer cells, obASCs expressed higher levels of CAF markers, including NG2, alpha-SMA, VEGF, FAP, and FSP, compared to lnASCs." (PMID 29527228, 2017). "Studies have confirmed that FAP α plays multiple roles in neoangiogenesis, invasion, and metastasis; thus, FAP α has been explored as a target for cancer therapy." (PMID 26985769, 2016). "Therefore, targeting FAP+ stromal cells may be a promising strategy to combat cancer." (PMID 24605102, 2014). "Because β1-integrins are major receptors responsible for ECM assembly, these results suggest that FAP remodels ECM fibers to provide directional paths for pancreatic (and other cancer, i.e., breast) cells to engage β1-integrin/FAK for invasion." (PMID 21668992, 2011). "In this work, we provide evidence that FAP is important for remodeling a permissive stromal ECM that supports pancreatic (and perhaps also breast) cancer invasion in vitro." (PMID 21668992, 2011). "When comparing absolute SUV, our findings are consistent with previously reported cases of FAP PET imaging using [68Ga]Ga-FAPI-04 in a larger RCC cohort (SUVmax, 3.1 vs. 3.2), and a comparison with 28 types of cancer revealed RCC to have the lowest uptake, comparable to our results." (PMID 41101974, 2026).
cancer (continued). "Fibroblast activation protein (FAP) is an attractive stromal target for cancer theranostics; however, developing agents that enable non-invasive pharmacokinetic visualization while achieving effective combined radio-chemotherapy remains challenging." (PMID 41944234, 2026). "As a pan‐cancer target, FAP holds significant potential and should not be overlooked in the development of precision cancer therapies." (PMID 40656546, 2025). "On the other hand, several cancer types do not induce a strong and/or consistent FAP uptake such as lymphoma, myeloma, prostate adenocarcinoma, renal cell carcinoma, melanoma and seminoma." (PMID 39572227, 2025). "In addition to AFP detection, fibroblast activation protein alpha (FAP-α) and carcinoembryonic antigen (CEA) are also important biomarkers in cancer diagnosis." (PMID 40942360, 2025). "However, FAP inhibitors radiolabelled with 68Ga, e.g., [68Ga]Ga-FAPI-46, are informative for the diagnosis and staging of several cancer types." (PMID 41049848, 2025). "FAP concentrations before and after radiation therapy as well as ΔFAP were independent of cancer type and not different in patients with or without concomitant chemotherapy." (PMID 40690098, 2025). "In our study, baseline and post-radiation FAP concentrations did not predict mortality in cancer patients undergoing radiation therapy." (PMID 40690098, 2025). "This investigation aims to describe the characteristics of 18F-FAPI-04 PET/CT of PM in different types of primary malignant tumors by comparing with those in 18F-FDG PET/CT, and preliminary explore the relationship between 18F-FAPI-04 PET/CT findings and the expression of FAP." (PMID 40457405, 2025). "FAP concentrations were not influenced by cancer type, radiation dose or chemotherapy and did not predict patient survival." (PMID 40690098, 2025). "FAP+ CAF-induced immune suppression could also be mediated through the CXCL12-CXCR4 axis, and inhibition of CXCR4 resulted in eradication of cancer cells by increasing intratumoral CD8+ T cells." (PMID 39780187, 2025). "The discovery of cancer-associated fibroblasts (CAFs) in the GB TME and the expression of FAP in both GB cells and non-malignant stromal cells within the TME, makes FAP an attractive target for radiopharmaceuticals 192,193." (PMID 40303349, 2025). "FAP-targeted NIR-PIT was more effective in immunocompetent mice than in athymic mice, suggesting that this therapy has both direct anti-cancer effects but also depends on activating the immune response by decreasing Tregs and increasing cytotoxic T cells in the TME." (PMID 38555315, 2024). "Notably, the expression of integrin αvβ6 in cancer cells activates TGF-β, which is positively correlated with increased levels of CAF markers such as α-SMA and fibroblast activation protein (FAP)." (PMID 38693104, 2024). "Considering that the Detox-iCAF cluster was the root of FAP+ CAF cluster trajectories, we hypothesized that the Detox-iCAF cluster could give rise to other FAP+ CAF clusters in presence of cancer cells." (PMID 38561380, 2024). "FAP was also the target with the largest percentage of patients with marker-high cancer tissue and marker-absent colon and liver normal tissues at 24% and 27%, respectively." (PMID 39335130, 2024). "BASP1, FAP, INHBA, and ITGA5 had been reported to be upregulated in several cancers and could regulate neuronal activity, but their relationship with DKK1, nerves, and HNSCC still remains unknown." (PMID 38525111, 2024). "Currently mainly human cancer cell lines transduced to (over)express FAP are applied, lacking clinical representation." (PMID 39718718, 2024). "Based on this analysis, FAP had the highest proportion of scorable patients with marker-present cancer and marker-absent adjacent normal tissue (91.4%)." (PMID 39335130, 2024).
cancer (continued). "While our studies point towards FAP as an ideal general target for CRC due to its low expression in normal tissues, many of the markers evaluated still display relatively low expression in normal tissues and high expression in cancer tissues." (PMID 39335130, 2024). "Unexpectedly, FAP and VIM were not as highly associated with SPARC expression in the cancer stroma of BC tumors and exhibited low expression." (PMID 39335478, 2024). "It was also tested for FAP and GRPR, which are other emerging targets for RPT in cancer." (PMID 39629134, 2024). "High FAP expression negatively correlated with CD8+ T cell infiltration in tumors including BRCA, CESC, HNSC, and SKCM but positively correlated with regulatory T cells in cancers such as LIHC, PCPG, PRAD, and THCA." (PMID 39055892, 2024). "The transcriptomic analysis confirmed mRNA expression of classical epithelial markers (cytokeratins, claudins, EpCAM, E-cadherin) in the SW480 cancer cell mono-spheroids and typical fibroblast markers (ACTA2/α-SMA, FAP-α, PDGFR, and MRC2) in the fibroblast mono-spheroids." (PMID 39011470, 2024). "The Cancers, another Zone-1 journal, emphasized FAP expression in malignant tumors and non-radioactive drug treatment; over half of these articles were reviews, including some on radiolabeled FAPIs." (PMID 39758423, 2024). "Contemporary strategies encompass TCVs targeting the CAF-activating protein FAP, CAR-T cell therapies, oncolytic viruses targeting CAFs, inhibiting cancer cell mechanotransduction to reduce TGF-β secretion, and focusing on pathways such as CXCL12-CXCR4, JAK-STAT3, and Hedgehog." (PMID 38693104, 2024). "The FAP regulates the focal adhesion kinase (FAK) pathway by reducing the phosphorylation of FAK, leading to the increased number of focal adhesions, affecting the direction of migration in cancer cells." (PMID 39579201, 2024). "Consistent with the spatial organization of these FAP+ CAF cluster-related ECT, we observe that cancer cells promote the differentiation of the Detox-iCAF cluster into Wound-myCAF and ECM-myCAF clusters through DPP4- and YAP1-dependent mechanisms both in vitro and in vivo." (PMID 38561380, 2024). "Importantly, it has paved the way for the development of radiotracers for quinoline-based FAP inhibitors (FAPIs), which are currently among the most promising radiotracers for PET imaging in cancer." (PMID 39758423, 2024). "FAP was expressed highly by 55.8% of cancer samples and was nearly absent in 93% of normal colon and liver samples." (PMID 39335130, 2024). "Evidence suggests that FAP is involved in cancer development through its enzymatic or non-enzymatic activity." (PMID 39055892, 2024). "Additionally, FAP has been found to be expressed on some CRC cancer cells, adding to its potential as a cancer target." (PMID 39335130, 2024). "Under hypoxic conditions, HCC cells can acquire CAF properties by the influence of cytokines and TGF-β which leads to an increase in the expression of FAP and α-SMA, generates mesenchymal cells that resemble fibroblasts, and subsequently contributes to chronic tissue fibrosis and cancer progression." (PMID 37035187, 2023). "In addition, significant correlation between FAP and immune check-points, MSI and TMB also suggested that FAP was involved in cancer immunology." (PMID 37325617, 2023). "We hypothesized the existence of a positive feedback loop between FAP and STAT3, which may have implications for developing new approaches in cancer therapy." (PMID 36825204, 2023). "A recent study identified two types of CAF subsets, MYH11+ αSMA+ CAF and FAP+ αSMA+ CAF, which contribute to T-cell exclusion and could restrict T cells contact with cancer cells." (PMID 37173705, 2023).